ESRP1 (epithelial splicing regulatory protein 1)
Diseases named in the same sentence as ESRP1 in open-access papers (continued):
Sharing a sentence is not in itself a finding about the gene and the disease.
prostate carcinoma (continued). "We detected similar splicing switches for 35/44 of these skipped exons after jointly depleting ESRP1 and 2 from the AR-positive CWR22 RV1 prostate cancer cell line." (PMID 31478829, 2019). "(B) Real-time PCR analysis of ESRP1 and ESRP2 mRNA from normal and matched prostate cancer tissue from nine patients obtained from radical prostatectomy." (PMID 31478829, 2019). "(A) Analysis of RNAseq data from human prostate cancer pre- and post- androgen deprivation therapy (ADT) shows that there is a significant downregulation of ESRP1 and ESRP2 mRNA following ADT in all seven patients tested (p=6e-04, Mann Whitney U test)." (PMID 31478829, 2019). "Future work will be needed to more precisely identify the genes controlled by ESRP1 and ESRP2 that are important in aggressive prostate cancer, how they result in tumour growth, and how expression of these genes are modulated in response to ADT and during tumour metastasis." (PMID 37752235, 2023). "This means that immunohistochemical analyses linking ESRP1 and ESRP2 expression with more aggressive disease progression might also be useful as prostate cancer biomarkers to apply in parallel to Gleason grading." (PMID 37752235, 2023). "Hence expression changes in ESRP1 and ESRP2 in clinical prostate cancer disease progression, and downstream modulation of mRNA splicing patterns, most likely occur within the broader context of global changes taking place in the splicing environment." (PMID 37752235, 2023). "Mechanistically, we found that epithelial splicing regulator proteins (ESRP1 and ESRP2) are the splicing factor through which AR may regulate splicing of pre-mRNA in prostate cancer cells." (PMID 32820253, 2020). "Further analyses supported androgen-mediated control of ESRP2 but not ESRP1 in prostate cancer cell lines." (PMID 31478829, 2019). "We next monitored ESRP1 and ESRP2 expression profiles from prostate cancer patients." (PMID 31478829, 2019). "In this same prostate cancer cohort, there were also frequent CNGs of MTDH and ESRP1." (PMID 27029057, 2016). "However, arguing against this indirect model, other immunohistochemical analyses have shown that higher levels of ESRP1 protein correlate with a shorter time to prostate cancer biochemical recurrence independent of ERG translocation status." (PMID 37752235, 2023). "However, contrary to the negative prognostic significance of ESRP1, ESRP1 has been shown to inhibit the growth of prostate cancer xenografts using androgen receptor-negative prostate cancer cells in vivo." (PMID 38110955, 2023). "Furthermore, the genomic inhibition of ESRP1/2 in prostate cancer cells did not affect the expression of E-cadherin and vimentin, key genes involved in EMT." (PMID 32820253, 2020). "Other prostate cancer studies on ESRP1 or ESRP2 IHC expression are so far lacking." (PMID 33339518, 2020). "As an example, in prostate cancer rearrangements occurred between untranslated exon 1 of SLC45A3 (a prostate-specific androgen responsive gene) and exon 8 of BRAF (GenBank GU149303) or between exon 13 of ESRP1 (an epithelial splicing regulatory protein) and exon 6 of RAF1 (GenBank GU149302)." (PMID 25473895, 2015). "Thus, upregulation of ESRP1/ESRP2 gene expression in aggressive tumours, by either gene amplification or in response to androgens could be different means to the same end, and drive the progression of aggressive prostate cancer in a similar way." (PMID 37752235, 2023). "However, whether ESRP1/2 regulates EMT or invasion of prostate cancer cells has not been established." (PMID 32820253, 2020). "Ectopic expression of ESRP1 and ESRP2 protein expression in AR negative PC3 and DU145 cell line models reduced prostate cancer cell growth in vitro." (PMID 31478829, 2019). "Western blots detected high endogenous levels of both ESRP1 and ESRP2 proteins within the AR positive LNCaP and CWR22 RV1 prostate cancer cell lines, as compared to the AR negative PC3 and DU145 prostate cancer cell lines." (PMID 31478829, 2019).
prostate carcinoma (continued). "For ETS fusion-negative prostate cancers subtypes, novel gene fusions have also been identified, including SLC45A3:BRAF, ESRP1:RAF1, SLC45A3:BRAF, ESRP1:RAF1, C15orf21:Myc, EPB41:BRAF, and TMEM79:SMG5." (PMID 23957008, 2013). "This implies that ESRP1 and ESRP2 may have different biological functions and are regulated differently in some instances, as recently reported in prostate cancer, where ESRP2 but not ESRP1 is regulated by androgens." (PMID 34520622, 2022).
gastric cancer (11 papers, 2019 to 2025). A primary or metastatic malignant neoplasm involving the stomach. "An interrogation of the gastric cancer data sets in TCGA was performed to examine the correlation between the expression of ESRP1 and LRRFIP2 variant 3 in metastatic progression." (PMID 36307405, 2022). "The expression level of ESRP1 may be related to prognosis in gastric cancer, with its overexpression possibly associated with malignancy and poor prognosis in gastric cancer, while its low expression may be associated with improved prognosis in gastric cancer." (PMID 40046628, 2025). "We next examined the effect of ESRP1 regulation on LRRFIP2 variant changes in gastric cancer." (PMID 36307405, 2022). "Knockdown of DHCR7 rescued the reduced proliferation of DGC cells due to overexpression of ESRP1, and also rescued the clone-forming ability of ESRP1 on gastric cancer cells." (PMID 40528239, 2025). "In gastric cancer, previous study has shown that 85% of patients presenting low ESRP1 expression were of diffuse type." (PMID 40528239, 2025). "LRRFIP2 expression is higher in high ESRP1-expressing cell lines, while LRRFIP variant 3 is higher in low ESRP1-expressing cell lines, determining gastric cancer cell metastasis via differential protein interaction with methyltransferase CARM1." (PMID 40046628, 2025). "The experimental results suggest that lncRNA CCAT2 upregulates the expression of CD44v6 by binding to ESRP1, thereby mediating the selective splicing of CD44 and promoting the development of gastric cancer, which is associated with shorter patient survival." (PMID 40046628, 2025). "Another study revealed an inverse correlation between ESRP1 levels and metastatic potential, with significantly reduced ESRP1 expression observed in gastric cancer patients with lymph node or distant metastases compared to non-metastatic cases." (PMID 40528239, 2025). "To identify the role of ESRP1 in regulating the invasiveness and motility of diffuse-gastric cancer cells, we conducted Transwell migration and Matrigel invasion assays using MKN45 cells." (PMID 40528239, 2025). "Consistently, overexpression of ESRP1 lead to decreased β-catenin protein in SGC7901 gastric cancer cells." (PMID 38114495, 2023). "Our results highlight the relationship between ESRP1 and gastric cancer metastasis, elucidating a novel CLSTN1-mediated invasion and metastasis mechanism." (PMID 38114495, 2023). "The rescue assay showed that knocking down CLSTN1-S significantly reversed the ESRP1-induced reduction in migration and invasion of gastric cancer cells in the transwell assay." (PMID 38114495, 2023). "In this study, we confirmed that ESRP1, an RNA-binding protein, can inhibit epithelial-mesenchymal transition and metastasis of gastric cancer by promoting alternative splicing of exon 11 of CLSTN1 mRNA." (PMID 38114495, 2023). "In gastric cancer, it has been reported that ESRP1 can promote exon 7 splicing of LRRFIP2 and inhibit migration and invasion." (PMID 38114495, 2023). "A deeper understanding of the molecular regulation of ESRP1-CLSTN1 will facilitate the design of new strategies to treat or prevent metastasis of gastric cancer." (PMID 38114495, 2023). "In this study, ESRP1 was found to decrease the migration and invasion of gastric cancer cells, suggesting the tumor-suppressive role of ESRP1." (PMID 38110955, 2023). "Nevertheless, our study provides new evidence and insights for ESRP1 to inhibit invasion and migration of gastric cancer, thus enriching its mechanism." (PMID 38114495, 2023). "ESRP1 is negatively correlated with distant metastasis and lymph node metastasis in gastric cancer patients." (PMID 38114495, 2023). "Transwell experiments showed that gastric cancer cells’ migration and invasion capacities decreased after overexpression of ESRP1." (PMID 38114495, 2023). "We then verified the relationship of ESRP1 expression and gastric cancer metastasis in TCGA database." (PMID 38114495, 2023).
gastric cancer (continued). "To further investigate the specific mechanism by which ESRP1 inhibits the metastasis of gastric cancer, we performed RNA sequencing on SGC7901 cells with ESRP1 or Vector overexpression." (PMID 38114495, 2023). "In gastric cancer, previous study has shown that 85% of gastric cancer patients with low ESRP1 expression have disseminated gastric cancer." (PMID 38114495, 2023). "Our study highlights the role of ESRP1 in regulating metastasis of gastric cancer and extends its mechanism." (PMID 38114495, 2023). "And we demonstrated that ESRP1 inhibit migration and invasion of gastric cancer in vitro and in vivo." (PMID 38114495, 2023). "In this study, we focused on the function of ESRP1 in gastric cancer and attempted to explore the regulation network of ESRP1." (PMID 38114495, 2023). "To further verify the influence of ESRP1 on metastasis of gastric cancer, we constructed two gastric cancer cell lines with overexpression of ESRP1 based on SGC7901 and BGC823, which have low endogenous ESRP1 expression levels." (PMID 38114495, 2023). "In this study, we further explored the mechanism of ESRP1 inhibiting metastasis of gastric cancer through CLIP sequencing." (PMID 38114495, 2023). "CAPZA1 promoted the expression of CD44 and epithelial splicing regulatory protein 1 (ESRP1), the latter which spliced CD44 into CD44 variant 9 (CD44v9), a marker of gastric cancer stem-like cells." (PMID 36526626, 2022). "Taken together, we report LRRFIP2 as an alternative splicing target of ESRP1 in gastric cancer, which represents a regulatory mechanism of LRRFIP2 splicing variants in gastric cancer metastasis." (PMID 36307405, 2022). "Based on the expression level of ESRP1 in 18 gastric cancer cell lines, we divided them into two groups; ESRP1-low and -high." (PMID 36307405, 2022). "Of note, a significantly lower expression level of ESRP1 and a higher expression level of LRRFIP2 variant 3 were observed in more advanced gastric cancer stages." (PMID 36307405, 2022). "To determine the clinical relevance of ESRP1 in gastric cancer, we first correlated the gene expression levels with the overall survival." (PMID 36307405, 2022). "Taken together, these results suggest that the relative frequencies of LRRFIP2 isoform switching are highly correlated with the expression levels of ESRP1 in human gastric cancer cell lines and gastric patient tissues." (PMID 36307405, 2022). "The frequencies of LRRFIP2 splicing events were directly correlated with the ESRP1 expression level, and the RNA sequencing results from the 18 gastric cancer cell lines and 18 tissue samples were confirmed by RT-PCR." (PMID 36307405, 2022). "Here, we show that epithelial and mesenchymal isoform switches of leucine-rich repeat Fli-I-interacting protein 2 (LRRFIP2) regulated by epithelial splicing regulatory protein 1 (ESRP1) correlate with metastatic potential of gastric cancer cells." (PMID 36307405, 2022). "Overall, amplification, and most likely promoter demethylation also, of FGFR2 and ESRP1 genes correlate well with higher expression levels of both genes in gastric cancers." (PMID 31881796, 2019). "However, the role and specific regulatory mechanisms of ESRP1 in gastric cancer, particularly in DGC, remain uncertain." (PMID 40528239, 2025). "To further evaluate the relationship between ESRP1 expression levels and the prognosis of patients with DGC, we stratified gastric cancer patients from gastric cancer public datasets into ESRP1-high and ESRP1-low expression subgroups based on the median cut-off value of ESRP1 expression." (PMID 40528239, 2025). "These may be the mechanisms by which ESRP1 inhibits gastric cancer metastasis through alternative splicing of CLSTN1." (PMID 38114495, 2023). "We also found that Ecadherin expression increased while Ncadherin decreased after overexpression of ESRP1 in gastric cancer cells, suggesting that ESRP1 may inhibit the EMT process." (PMID 38114495, 2023).
gastric cancer (continued). "Moreover, an increased interaction of β-catenin and Ecadherin was also observed in gastric cancer cells overexpressing ESRP1." (PMID 38114495, 2023). "Next, we further verified the role of ESRP1 in gastric cancer using our dataset." (PMID 38114495, 2023). "To further test this hypothesis, we knocked down CLSTN1-S (oeES-shCL-S) in gastric cancer cells overexpressing ESRP1." (PMID 38114495, 2023). "We collected 24 surgical specimens from gastric cancer patients and evaluated ESRP1 expression." (PMID 38114495, 2023). "In addition to LRRFIP2, CCDC50, another splicing candidate of ESRP1, also showed skipping exon event and BICD2 showed retained intron event occurring in gastric cancer cells depending on the expression of ESRP1." (PMID 36307405, 2022). "In addition to LRRFIP2, other splicing candidates of ESRP1 in gastric cancer cells have been discovered by our RNA sequencing analysis." (PMID 36307405, 2022). "In this study, based on transcript profiles and isoform switch analysis of 18 gastric cancer cells and 18 gastric patient tissues, we demonstrated the significant association between the expression of ESRP1 and the alternative splicing of LRRFIP2 in gastric cancer cells." (PMID 36307405, 2022). "The rescue experiments proved that knockdown of DHCR7 could be restored the effect of ESRP1 overexpression on proliferation, migration, invasion and ferroptosis of gastric cancer cells, indicating that ESRP1 inhibits DGC progression by promoting DHCR7-mediated ferroptosis." (PMID 40528239, 2025). "And ESRP1-induced isoform switching of LRRFIP2 may inhibit metastasis of gastric cancer." (PMID 38114495, 2023). "Although there are few studies about the roles of the splicing variants of these genes in gastric cancer, the correlations between the expression levels of ESRP1 and the relative frequencies of these variants in a set of gastric cancer cells and tissues have not been thoroughly examined until now." (PMID 36307405, 2022). "ESRP1 binds to lncRNA CCAT2, which regulates CD44 splicing, promoting the transition from standard CD44 to CD44v6 and facilitating gastric cancer progression." (PMID 40046628, 2025). "Studies have shown that ESRP1 is overexpressed in gastric cancer (GC)." (PMID 40046628, 2025). "Our study provides new insights into the molecular regulation of ESRP1-CLSTN1 and its role in gastric cancer metastasis." (PMID 38114495, 2023). "Here, we found that ESRP1, a RBP specific in epithelial cells, is important in regulating the metastasis of gastric cancer cells." (PMID 38114495, 2023). "Recently, ESRP1 was reported to regulate the isoform switch of LRRFIP2 and to determine the metastasis of gastric cancer." (PMID 38069324, 2023). "Our results demonstrate that ESRP1-mediated CLSTN1 exon 11 splicing can increase Ecadherin expression, thus inhibiting EMT in gastric cancer cells." (PMID 38114495, 2023). "In addition, we examined the effect of CLSTN1 on key EMT proteins and found that CLSTN1-S promoted Ecadherin protein expression and inhibited Ncadherin expression, while CLSTN1-F had the opposite effect, suggesting that CLSTN1-S may mediates ESRP1 induced inhibition of gastric cancer metastasis." (PMID 38114495, 2023). "We demonstrated that expression of ESRP1 was negatively correlated with lymph node metastasis, distant metastasis, and TNM stage in gastric cancer patients." (PMID 38114495, 2023). "In conclusion, our study confirmed that ESRP1 expression and CLSTN1 splicing level were negatively correlated with metastasis of gastric cancer in vitro, in vivo, and in clinical samples." (PMID 38114495, 2023). "Through PCR detection of 24 gastric cancer specimens, we found that the splicing ratio of CLSTN1 (CLSTN1-S/CLSTN1-F) was positively correlated with the expression level of ESRP1." (PMID 38114495, 2023). "Our results show that ESRP1-regulated CLSTN1 exon 11 alternative splicing also plays an important role in the invasion and metastasis of gastric cancer." (PMID 38114495, 2023).
gastric cancer (continued). "This emphasizes the potential of ESRP1 and CLSTN1 as attractive therapeutic targets in gastric cancer." (PMID 38114495, 2023). "We found that the exon 11 spliced transcript (CLSTN1-S) can inhibit invasion and migration of gastric cancer cells, and targeting CLSTN1-S can reverse ESRP1-induced invasion and migration inhibition." (PMID 38114495, 2023). "In this study, we demonstrate an alternative splicing target of ESRP1, leucine-rich repeat Fli-1-interacting protein 2 (LRRFIP2), in gastric cancer cells." (PMID 36307405, 2022). "RNA sequencing in a set of gastric cancer cell lines and gastric cancer patient tissues and isoform switch analysis using iso-KTSP15 provided a means to begin to interrogate ESRP1-induced alternative splicing events." (PMID 36307405, 2022). "Although accumulating evidence indicates the roles and clinical significance of ESRP1 in tumor progression and metastasis, the role and regulatory mechanisms of ESRP1 in gastric cancer, especially in DGC, have not been thoroughly studied." (PMID 40528239, 2025). "Of these DEGs, 40 RBPs were upregulated in metastatic gastric cancer, while 11 RBPs were highly expressed in non-metastatic gastric cancer, including ESRP1." (PMID 38114495, 2023). "We found that the expression of ESRP1 in gastric cancer patients without lymph node metastasis was significantly higher than in patients with lymph node metastasis." (PMID 38114495, 2023). "These may be key mechanisms by which ESRP1 and CLSTN1-S suppress metastasis of gastric cancer cells." (PMID 38114495, 2023). "Although accumulating evidence indicates the roles and clinical significance of ESRP1 and its alternative splicing targets in tumor progression and metastasis, ESRP1-regulated alternative splicing in gastric cancer has not yet been thoroughly studied." (PMID 36307405, 2022). "We found that ESRP1 drives CLSTN1 exon 11 splicing, resulting in the spliced CLSTN1 (short CLSTN1), which participates in inhibiting tumor cell EMT and stabilizing Ecadherin/β-catenin adhesive structure, which is an important mechanism for inhibiting gastric cancer metastasis." (PMID 38114495, 2023). "To identify the role of ESRP1 in regulating the invasiveness and motility of gastric cancer cells, we conducted transwell migration and Matrigel invasion assays using MKN1 cells, which have low basal expression of ESRP1, following ectopic overexpression of ESRP1." (PMID 36307405, 2022). "We further designed primers across exon 11 for verification and found that, after overexpression of ESRP1, the truncated product (exon 11 skipping, 103 bp) of CLSTN1 increased, while the full length (exon 11 no skipping, 160 bp) decreased in gastric cancer cells." (PMID 38114495, 2023).